FTO (FTO alpha-ketoglutarate dependent dioxygenase)
Diseases named in the same sentence as FTO in open-access papers (continued):
Sharing a sentence is not in itself a finding about the gene and the disease.
infection (29 papers, 2013 to 2025). The state of being infected such as from the introduction of a foreign agent such as serum, vaccine, antigenic substance or organism. "However, FTO is essential for the protective function of CD8+ T cells against pathogenic infections." (PMID 40234389, 2025). "The results showed that mice transferred with FTO KO CD8+ T cells, compared to those with WT CD8+ T cells, had significantly increased bacterial colonies on agar plates in both spleen and liver, suggesting that FTO-deficient CD8+ T cells had impaired effector function against infection." (PMID 40234389, 2025). "Compared to an equal number transferred on day 0, the ratio of FTO KO to WT OT-1+CD8+ T cells was significantly reduced in peripheral blood lymphocytes (PBL) following infection, strongly suggesting that FTO-deficient CD8+ T cells had a diminished immune response." (PMID 40234389, 2025). "Here, by T cell-specific deletion of FTO, we unveiled that FTO was crucial for supporting CD8+ T cell immune response and protective function during pathogenic infection." (PMID 40234389, 2025). "The western blotting and qPCR analyses confirmed that the protein expression of FTO was reduced in macrophages after infection with S. aureus, consistent with the observed changes in mRNA expression." (PMID 39980685, 2025). "Overall, these data confirm that FTO is inhibited as a result of infection with the FTO shRNA-expressing lentivirus, based on both the western blot and the substantial increases in m6Am stoichiometry in snRNAs." (PMID 41279954, 2025). "Knocking-down of FTO retarded the infection induced-decrease in the levels of m6A modification in TNF-α transcripts, accompanied by dampened immune response and uncontrolled T. gondii proliferation." (PMID 40663568, 2025). "Accordingly, the Fas expression was significantly elevated in FTO-deficient OT-1+CD8+ T cells, compared to WT counterparts, in the in vivo co-transfer model on days 4 and 5 post-infection." (PMID 40234389, 2025). "Knocking-down FTO hindered the infection-induced decrease in m6A modification levels of TNF-α transcripts, accompanied by a dampened immune response and uncontrolled T. gondii proliferation." (PMID 40663568, 2025). "In this study, we unveil that infection of cells with the porcine alphaherpesvirus PRV leads to phosphorylation of the m6A(m) demethylase FTO." (PMID 39791911, 2025). "Curiously, HCMV infection is also associated with increased levels of the m6A eraser proteins FTO and ALKBH5 late in infection in human fibroblasts." (PMID 39868828, 2025). "Noteworthy, the number of copies of the viral RNA 6 h post infection was similar when comparing the control condition against treatments with the viral polymerase inhibitor Gemcitabine or the FTO inhibitor MA." (PMID 39744389, 2024). "The FTO inhibitor reduced CVB1 expression within 6 h post-infection, suggesting a direct regulation of the CVB1 genome by m6A modification." (PMID 39744389, 2024). "Time course experiments indicate that CVB1 translation and replication are delayed in the presence of FTO inhibitor within hours post infection, indicating a direct effect of FTO on the RNA viral genome." (PMID 39744389, 2024). "Conversely, infection with a lentiviral FTO RNAi construct led to significantly decreased FTO expression." (PMID 37569302, 2023). "As expected, the activity of the reporter containing these sites increased after Ad-FTO infection and decreased after siFTO transfection." (PMID 36352530, 2023). "In a HFD-induced NAFLD mouse model, infection with an adenovirus expressing FTO (ad-FTO) increased mRNA and protein expression of SREBF1 and ChREBP." (PMID 37628704, 2023). "Consistently, a reporter containing these sites showed increased activity after Ad-FTO infection and lower activity after FTO knockdown, suggesting that FTO binding on these three m6A sites of SREBF1 increased its expression." (PMID 36352530, 2023).
infection (continued). "The results of qRT-PCR showed that FTO expression was significantly increased following infection of primary hepatocytes with a lentiviral FTO overexpression construct." (PMID 37569302, 2023). "Consistent with these in vivo findings, Ad-FTO infection upregulated the mRNA levels of key lipogenic genes in HepG2 and Hepa1-6 cells in vitro." (PMID 36352530, 2023). "Starting with m6A-related enzymes, such as FTO, it will be of great significance to explore the influence of m6A on the replication and infection mechanism of SFTSV and provide new avenues for the treatment of SFTS." (PMID 34561445, 2021). "The adenoviral particles carrying FTO cDNA infection resulted in substantial upregulation of FTO in SCC25‐A‐shFTO and CAL27‐A‐shFTO cells." (PMID 34378866, 2021). "We used siRNA to knockdown either ALKBH5 or FTO in A549 cells and performed a time-course infection with Ad5." (PMID 33243990, 2020). "Depletion of METTL3 or METTL14 enhanced ZIKV infection in 293T cells whereas ALKBH5 and, to a lesser extent, FTO knockdown reduced infection." (PMID 29259584, 2017). "Intriguingly, knockdown of METTL3/14 enhanced infection while FTO depletion correspondingly reduced infection." (PMID 29259584, 2017). "Upon infection at an MOI of 0.1 and 1, PRV-induced phosphorylation of FTO could be detected at 16 and 24 hpi, while infection at an MOI of 10 phosphorylation triggers detectable FTO phosphorylation already at 6 hpi." (PMID 39791911, 2025). "Furthermore, to evaluate the impact of FTO on endogenous CD8+ T cell responses, we conducted a direct infection model on WT and FTO conditional KO mice." (PMID 40234389, 2025). "Furthermore, Western blot experiments confirmed that FTO protein expression was reduced in macrophages after infection with S. aureus at an MOI of 10, which was consistent with the observed changes in mRNA expression." (PMID 39980685, 2025). "With increasing duration of infection, the expression of FTO was significantly higher in Cag A+H." (PMID 36918410, 2023). "However, METTL3, METTL14, WTAP, ALKBH5, and FTO were all present in both the nucleus and cytoplasm after infection." (PMID 34225491, 2021). "Moreover, the key m6A demethylation gene FTO exhibited a tendency of high expression after SFTSV infection, which was consistent with the significant decrease in the abundance of the m6A peaks observed in m6A-seq." (PMID 34561445, 2021). "Next, we knocked down ALKBH5 or FTO, or both, in HeLa cells, followed by rgRSV infection." (PMID 31597913, 2019). "Interestingly, the inhibition of FTO leads to a delayed expression and replication of the viral genome at early time points but drastically impairs the production of infectious virus at 24 h post infection." (PMID 39744389, 2024). "Following infection with S. aureus at an MOI of 10, the FTO expression in macrophages was statistically significant." (PMID 39980685, 2025). "In the in vivo co-transfer model, FTO KO CD8+ T cells had significantly increased expression levels of Annexin V and 7AAD on both day 4 and 5 post-infection." (PMID 40234389, 2025). "In keeping with these findings, the mRNA levels of METTL3 & METTL14 (m6A writers), ALKBH5 & FTO (m6A erasers), and YTHDF2 (m6A reader) were significantly increased in a time-dependent fashion in Huh7 cells post SFTSV infection." (PMID 39585899, 2024). "To investigate how oHSV promotes NETosis, we found that oHSV infection increased IGF2BP3 and MIB1 expression while suppressing FTO in a time-dependent manner, along with the detection of viral proteins ICP0, ICP8, and gC." (PMID 38167409, 2024). "Immunoblotting with antibodies targeting ALKBH5, FTO, METTL14 and METTL3 in ileum tissue from mice infected with RV EW or treated with PBS was carried out at 2 days post infection (dpi)." (PMID 35098923, 2022).
infection (continued). "In an in vivo acute infection model, naïve CD8+ T cells from WT (Ftofl/flCD4-Cre−OT-1+, CD45.1+) and FTO KO (Ftofl/flCD4-Cre+OT-1+, CD45.2+) mice were transferred separately into the WT recipient mice (CD45.1+CD45.2+) followed by infection with Listeria monocytogenes (LM) expressing OVA (LM-OVA)." (PMID 40234389, 2025). "Infection of ST cells with a mutant virus that does not express US3 yielded similar levels of FTO phosphorylation compared to WT infection." (PMID 39791911, 2025). "We noted a slight decrease in METTL3 and METTL14 protein levels at 36 h post-infection (hpi), whereas the protein levels of FTO and ALKBH5 did not significantly change during CVB3 infection." (PMID 39339923, 2024). "However, infection with a virus mutated in the UL13 gene failed to induce the accumulation of phosphorylated FTO, indicating that the viral UL13 kinase is required for FTO phosphorylation." (PMID 39791911, 2025). "However, FTO knockdown did not substantially affect viral protein expression upon infection." (PMID 39791911, 2025). "The expression of the demethylase FTO decreased at 48 hpi, whereas that of ALKBH5 was not changed after infection." (PMID 34225491, 2021).
kidney diseases (15 papers, 2010 to 2025). "However, we also observed the alteration of other major m6A modifying enzymes, such as METTL3 and FTO, in proteinuric kidney disease models." (PMID 34580283, 2021). "METTL3, METTL14 and FTO may play major roles in interstitial fibrosis during UUO nephropathy." (PMID 38066436, 2023). "Moreover, METTL3 is more closely associated with kidney disease than METTL14 and FTO, although there are already related drugs to improve renal function and treat renal diseases through METTL3, more in-depth research and exploration can be carried out in this aspect in the future." (PMID 38066436, 2023). "There are currently 24 known m6A regulatory proteins, but studies on m6A methylation in kidney disease have been limited to four to five enzymes such as METTL14, METTL3 and FTO, and there have been few studies on other enzymes." (PMID 38066436, 2023).
neurological disorders (12 papers, 2009 to 2025). "Further studies are needed to determine whether FTO transgenic mice display resistance or reduced sensitivity to chronic-arsenic-exposure-caused neurological disorders." (PMID 36233132, 2022). "In addition, SNPs within the FTO gene could be associated with neurological disorders such as Alzheimer’s and depression." (PMID 30730976, 2019). "FTO, a demethylase involved in the removal of the m6A modification from mRNA, has established roles in normal central nervous system functions and the pathobiology of neurological disorders." (PMID 38092760, 2023). "In addition, changes in FTO expression in various diseases suggest a possible link between lipid metabolism and neurological diseases." (PMID 36009052, 2022). "Together these results suggest that FTO may be a possible new target to find novel approaches for the treatment of neurological diseases via regulating BDNF processing." (PMID 30730976, 2019). "Independent of fatness, the A-allele of the FTO SNP appears to increase mortality of a magnitude similar to smoking, but without a particular underlying disease pattern barring an increase in the risk of diseases of the nervous system." (PMID 19214238, 2009).
neurodegenerative disease (10 papers, 2015 to 2026). A disorder of the central nervous system characterized by gradual and progressive loss of neural tissue and neurologic function. "Targeting FTO with MO-I-500 could thus achieve simultaneous protective effects in both astrocytes and neurons, offering a novel approach to combat age-associated neurodegenerative diseases." (PMID 41602161, 2026). "Research has shown that in models of neurodegenerative diseases, FTO affects the survival of neurons by regulating the m6A status of Nrf2." (PMID 39875055, 2025). "For example, m6A machinery, but not m6A itself, has been implicated in some neurodegenerative diseases: single nucleotide polymorphisms in FTO have been implicated in many neuropsychiatric diseases." (PMID 33402207, 2021). "Milk-miRNA-29-mediated suppression of DNA methylation and FTO-enhanced mRNA m6A demethylation via persistent milk consumption may thus play an important role in the pathogenesis of neurodegenerative diseases." (PMID 26691922, 2015).
heart disease (7 papers, 2017 to 2024). "In the mediation and moderation analyses (eFigure 2 in Supplement 1), only FTO LD block 2 had significant direct effects on heart disease among Black participants (c′ = 0.145 [SE, 0.0517]; P = .01), not mediated through BMI or WHtR." (PMID 38064210, 2023). "Current knowledge suggests that FTO plays a comprehensive role in cardiovascular health, impacting processes from the initial development of heart tissue to heart disease progression, making FTO an intriguing molecular target for potential clinical interventions." (PMID 39744011, 2024). "Fat mass and obesity-associated protein (FTO), an N6-methyladenosine (m6A) demethylase, and methyltransferase-like 3 (METTL3), an m6A methyltransferase, are pivotal regulators in the methylation landscape associated with heart diseases." (PMID 39334823, 2024).
inflammation (5 papers, 2021 to 2025). Aberrant reaction of the microcirculation characterized by movement of fluid and leukocytes from the blood into extravascular tissues. "Conversely, loss-of-function of FTO inhibited palmitic acid-induced cardiac inflammation and altered CD36 expression by diminishing the stability of CD36 mRNA." (PMID 34881240, 2021). "Growing evidence revealed the critical role of retinal inflammation in impaired endothelial function, vascular leakage, pericyte loss and retinal neovascularization, we therefore tested whether FTO associates with vascular inflammation." (PMID 38297099, 2024). "We further identified that FTO facilitates angiogenesis, triggers diabetic microvascular leakage, and induces retinal inflammation and neurodegeneration in DR." (PMID 38297099, 2024). "To further confirm the expression of METTL14, WTAP, METTL3, FTO and ALKBH5 in NPC tissues, we utilized RT‐qPCR to detect their expression in 28 NPC tissues and 7 nasopharyngeal chronic inflammation tissues." (PMID 39021049, 2024).
liver (4 papers, 2022 to 2025). "When we reduced the locus radius from 1MB to 500KB and re-ran the analysis, both TGVIS and TGFM identified the sGene of FTO-Pancreas as causal, with CS-Pratt values of 0.345 and 0.407, respectively." (PMID 39711576, 2024).
bacterial infection (2 papers, 2022 to 2023). "Therefore, both METTL14 activation and FTO reduction work together to increase m6A levels upon bacterial infection or LPS treatment." (PMID 36864027, 2023).
blood cancers (2 papers, 2022). "Unlike ALKBH5, FTO expression in MM was not high compared with other blood cancers and solid tumors." (PMID 34759347, 2022).
brain diseases (2 papers, 2022 to 2025). "Hence, FTO could be a valuable therapeutic target for brain diseases in the future." (PMID 36163017, 2022).
hematological malignancies (2 papers, 2019 to 2022). "Similar to FTO inhibitors, METTL3 inhibitors have been produced and studied in recent years, and they will be a potent potential target to treat patients with hematological malignancies in the future, especially AML and chemoresistant CML." (PMID 35574332, 2022).
adenocarcinoma (1 paper, 2022). A common cancer characterized by the presence of malignant glandular cells. "In addition, FTO expression was also up-regulated in 89 adenocarcinoma specimens, but without significant difference." (PMID 35524932, 2022).
CNS tumor (1 paper, 2021). "Of note, our previous study indicated that FTO gene SNPs are unlikely to have significant effects on CNS tumor risk." (PMID 35201446, 2021).
gynecological tumors (1 paper, 2024). "Investigating FTO’s utility as a biomarker for the diagnosis and prognosis of gynecological tumors, along with its safety, efficacy, specificity, and sensitivity, is imperative." (PMID 39175477, 2024).
malformation syndrome (1 paper, 2023). "Similarly, the mutation Arg322Gln also renders FTO inactive and is known to be associated with malformation syndrome, an autosomal recessive disorder." (PMID 36717943, 2023).
FTO also shares sentences with these, for which no sentence is quoted: type 1 diabetes (9 papers); Hyperinsulinemia (4); hypertriglyceridemia (4); periodontitis (4); retinopathy (4); acute promyelocytic leukemia (3); amyotrophic lateral sclerosis (3); fetal growth restriction (3); kidney cancer (3); skin cancer (3); alcoholism (2); aortic aneurysm (2); aortic valve stenosis (2); Arthritis (2); bulimia nervosa (2); chronic obstructive pulmonary disease (2); cutaneous squamous cell carcinoma (2); endometrial tumor (2); hearing loss (2); Hypercholesterolemia (2); hypopharyngeal squamous cell carcinoma (2); hypothyroidism (2); infectious disease (2); juvenile idiopathic arthritis (2); kidney failure (2); multiple sclerosis (2); pancreatic neuroendocrine neoplasm (2); pulmonary arterial hypertension (2); rectum adenocarcinoma (2); squamous cell carcinoma (2).
A further 99 diseases each share a sentence with FTO in 1 paper.